MET (MET proto-oncogene, receptor tyrosine kinase)
Diseases named in the same sentence as MET in open-access papers (continued):
Sharing a sentence is not in itself a finding about the gene and the disease.
lung cancer (continued). "MET amplification has been reported to induce gefitinib resistance via ErbB3 in EGFR mutant lung cancers." (PMID 26919104, 2016). "Collectively, we discovered miR-329 targeted 3′-UTR of MET, and inhibited the expression levels of c-Met in lung cancer cell lines (A549 and H1299)." (PMID 26909600, 2016). "In this study, we identified a subset of patients harboring MET exon 14 skipping as a novel oncogenic driver in lung cancers." (PMID 27223439, 2016). "Crosstalk between EGFR and MET has been implicated in therapeutic resistance to EGFR inhibitors in colon and lung cancers." (PMID 27655711, 2016). "Recurrent MET exon 14 splicing has been revealed in lung cancers and is a promising therapeutic target." (PMID 27223439, 2016). "In this study, we show for the first time that miR-329 directly targets and regulates the full-length 3′-UTR of the human MET mRNA, which is up-regulated in many cancers, including lung cancer." (PMID 26909600, 2016). "At present, crizotinib, a dual inhibitor of EML4-ALK and MET, already has been widely employed in lung cancer patients harboring the EML4-ALK fusion." (PMID 26919104, 2016). "Collectively, our results demonstrated that miR-329 played a pivotal role in lung cancer through inhibiting cell proliferation, migration, invasion, and promoting apoptosis by targeting oncogenic MET." (PMID 26909600, 2016). "A study revealed that HGF activated the MET-ERK pathway, inducing resistance to erlotinib in an EGFR-mutated lung cancer cell line, KHM-3S, and the sensitivity of erlotinib was restored by crizotinib." (PMID 27331411, 2016). "This was noted in studies of MET amplified lung cancer cells, which demonstrated that the formation of EGFR:MET and ErbB2:MET heterodimers rendered the EGFR family member resistant to dephosphorylation in the presence of their respective TKI." (PMID 27597943, 2016). "An in vivo study indicated that volitinib selectively inhibited the growth of MET-driven gastric and lung cancer cell line and primary tumor xenografts." (PMID 27013592, 2016). "Here, we demonstrated that MET exon 14 skipping is a novel oncogenic driver in lung cancers by clinical and pathological characteristics." (PMID 27223439, 2016). "A significantly positive correlation was observed between MET amplification and MET protein overexpression, in agreement with previous data in gastric and lung cancer." (PMID 25965822, 2015). "One signaling pathway that has been a focus of active research in lung cancer is the c-MET signaling pathway (3, –, 6)." (PMID 25925948, 2015). "With the use of this two-tier strategy, we reliably determined the frequency of EGFR mutations and EGFR, MET and ERBB2 amplifications in over 200 lung cancer samples." (PMID 25719557, 2015). "The evidence of miRNA participating in the EGFR/c-MET network in lung cancer thus provides a new clue to overcoming EGFR-TKI resistance in lung cancer." (PMID 26273639, 2015). "To conclude, in this study we report the frequency of EGFR mutations in a cohort of 956 lung cancer patients as well as the frequency of alterations in KRAS, BRAF, MET, PIK3CA and ALK genes in a subset of these patients." (PMID 26208325, 2015). "EGFR signaling has been shown to enhance HGF-induced c-MET phosphorylation levels in lung cancer cell lines." (PMID 26260789, 2015). "We had selected EBC1 lung cancer cells for our initial studies because they harbor amplification of MET, a receptor tyrosine kinase that mediates critical oncogenic signals through the PI3K/AKT axis." (PMID 25551293, 2014). "It has been reported that c-MET was highly expressed in a variety of carcinomas, including lung cancer, breast cancer, colon cancer, and pancreatic cancer." (PMID 25193856, 2014). "This antibody inhibits the growth and invasion of different tumor cell lines, and shows a potent anti-tumor effect in in vivo models of both HGF-dependent and HGF-independent MET activation, including a MET-amplified lung cancer xenopatient." (PMID 28548076, 2014).
lung cancer (continued). "So that we suppose that PAX6 activates MAPK signaling and promotes cell cycle progression via MET gene transcription in lung cancer." (PMID 24454925, 2014). "We previously reported that HGF induces EGFR-TKI-resistance in EGFR mutant lung cancer cells by restoring MET/PI3K/AKT pathway signaling." (PMID 23690929, 2013). "The dual MET-EGFR combinatorial inhibition is well-tolerated in advanced stage lung cancer patients." (PMID 27234388, 2013). "This inconsistence also occurred to miR-130a, which was shown to not only inhibit tumor suppressor RUNX3 in hepatocellular carcinoma but also suppress proto-oncogene MET in lung cancer." (PMID 23302469, 2013). "We also investigated the combination of EGFR TKIs (gefitinib, erlotinib or afatinib) or the monoclonal EGFR antibody cetuximab, with the c-MET inhibitor su11274 in the same set of lung cancer cell lines." (PMID 23527257, 2013). "For a subset of lung cancers with acquired resistance to epidermal growth factor receptor-targeting therapy, MET amplification is one of the most frequently involved mechanisms." (PMID 23379953, 2013). "One frequent characteristic of lung cancer is an aberration in which one or more receptor tyrosine kinases (RTKs), such as MET, EGFR, and ALK, are commonly overexpressed, amplified, or mutated." (PMID 23844053, 2013). "A recent randomized trial demonstrated that the combination of bexarotene (the first RXR-selective retinoid) with/tivantinib (a MET inhibitor) and erlotinib is effective as a treatment for KRAS-mutation-driven lung cancer and is well-tolerated." (PMID 23520448, 2013). "In this article, we review the four commonly known oncogenic driver mutations in lung cancer – EGFR mutations at exons 18 – 21, KRAS gene mutation at codons 12 and 13, EML4-ALK fusion genes and deregulation of MET signaling." (PMID 27234388, 2013). "EGF-receptor tyrosine kinase (TK) inhibitors, such as Gefitinib, are known to reduce lung carcinoma metastasis, but long-term use of Gefitinib leads to drug resistance via MET gene amplification or HGF-dependent pathway." (PMID 23296269, 2013). "EGFR tyrosine kinase inhibitors (EGF-TKI) intercept EGFR-mediated downstream signaling pathways (such as PI3K-AKT) via de-phosphorylation of Her3, while some lung carcinoma cell lines acquire resistance via amplification of MET." (PMID 23296269, 2013). "We characterized in detail 10 antibodies (designated LMH) that bound c-MET on the surface of A549 lung cancer cells as determined by FACS." (PMID 22511956, 2012). "MET amplification has been detected in lung cancer cell lines that have acquired resistance to gefitinib." (PMID 22992338, 2012). "Amplification of MET, a receptor tyrosine kinase, was detected in up to 20% of lung cancer specimens that developed acquired resistance to gefitinib or erlotinib." (PMID 22970367, 2012). "The anti-c-MET scFv showed a selective binding and internalization in several lung cancer cell lines expressing c-MET and in vivo fluorescent imaging by scFv-conjugated quantum dots showed higher tumor uptake and increased tumor to normal tissue ratios." (PMID 22606042, 2012). "To evaluate this further we examined these antibodies by IP in A549 lung cancer cells and LoVo colon cancer cells, the latter only expressing the p170 c-MET due to intrinsic defects in c-MET post-translational processing." (PMID 22511956, 2012). "More specifically, pathway genes that show associations with EGFR or MET were examined in detail, because EGFR and MET are among the best-studied growth signals in lung cancer patients." (PMID 22211244, 2012). "We have here shown that MET associates with EGFR, HER2, HER3, and RET, and that these heterodimerisation partners of MET are highly phosphorylated in lung cancer cells positive for MET amplification." (PMID 21847121, 2011).
lung cancer (continued). "We have now found that MET also forms a complex with HER3 in lung cancer cells with endogenous amplification of MET and that the heterodimer was dissociated as a result of inhibition of MET kinase activity." (PMID 21847121, 2011). "It is thus possible that trans-phosphorylated EGFR, HER2, HER3, and RET act as scaffold proteins to promote downstream signalling of MET in lung cancer cells with MET amplification." (PMID 21847121, 2011). "With the use of an RTK array, we identified phosphorylated RTKs in lung cancer cells with MET amplification." (PMID 21847121, 2011). "Taken together, these data thus suggest that the association between MET and these RTKs is dependent on MET kinase activity and results in their trans-phosphorylation by MET in lung cancer cells with MET amplification." (PMID 21847121, 2011). "Our study provides new insight into the functional roles of trans-phosphorylated RTKs in MET amplification-positive lung cancer." (PMID 21847121, 2011). "We further investigated the functional roles of these RTKs in lung cancer cells with MET amplification." (PMID 21847121, 2011). "In conclusion, our results suggest that EGFR, HER2, HER3, and RET are trans-phosphorylated by MET and promote cell proliferation and survival or cell migration as heterodimerisation partners of MET in lung cancer cells with MET amplification." (PMID 21847121, 2011). "For the initial assessment of antibody specificity, we used the lung cancer cell lines H1680 and H522 that express high and undetectable levels of c-MET, respectively." (PMID 21283737, 2011). "We investigated the roles and mechanisms of RTK heterodimerisation in lung cancer with MET amplification." (PMID 21847121, 2011). "To identify heterodimerisation partners of MET in lung cancer cells with MET amplification in a comprehensive manner, we made use of an RTK array." (PMID 21847121, 2011). "With the use of an RTK array, we found that EBC-1 and H1993, two human lung cancer cell lines with MET amplification, exhibited a high level of tyrosine phosphorylation of MET, EGFR, HER2, HER3, and RET under conditions of serum deprivation." (PMID 21847121, 2011). "MET amplification was found in 4 of 18 lung cancer biopsy samples obtained from patients with acquired resistance to gefitinib or erlotinib." (PMID 21165163, 2010). "More recently, MET amplification and activation via HGF/SF has also been implicated in resistance to EGFR inhibition in lung cancer." (PMID 21049054, 2010). "Conversely, 89.2% Taiwanese lung cancer patients have an identifiable mutation in either c-CBL, MET or EGFR or a combination of the three genes." (PMID 20126411, 2010). "That is, the smoking-gene interaction means that some smokers are at greater risk of developing lung cancer, with several host characteristics (i.e., K-ras, GSTM1, CYP2D6, c-MET, NKX2-1, LKB1, BRAF) implicated in lung cancer onset." (PMID 20843376, 2010). "Previous studies from our lab and others have shown that East Asians with lung cancers have relatively high frequencies of gain-of-function of mutations in RTKs such as EGFR and MET." (PMID 20126411, 2010). "The second major mechanism of acquired resistance reported is the amplification of the MET oncogene that activates ERBB3/PI3K/AKT signalling in lung cancer." (PMID 21165163, 2010). "Herein, we have identified that MET and PKCß are expressed in lung cancer, and their inhibition can be synergistic." (PMID 19955662, 2009). "Moreover, it would be useful to further investigate and catalogue the activating mechanisms of MET (such as activating mutations, transcriptional and protein overexpression), and their role in oncogenic signalling in the context of multiple receptor co-activation in lung cancer." (PMID 19238632, 2008). "We show that MET is highly expressed in lung cancer, often concomitantly with epidermal growth factor receptor (EGFR), including H1975 cell line." (PMID 19238632, 2008).
lung cancer (continued). "To further test the role of MET inhibition in EGFR-TKI-resistant lung cancer in vivo, we developed stable luciferase-expressing H1975 lung cancer cells using lentivirus transduction." (PMID 19238632, 2008). "Standard-of-care treatment of amplified MET-positive non–small cell lung cancer suggests that 63% (65/103) of MET-amplified positive pRCC might be eligible for capmatinib, crizotinib, or tenpotinib." (PMID 41563788, 2026). "MET knockdown sensitized resistant cells to EGF and reduced their anchorage-independent growth and migration, while combination therapy with a MET inhibitor and cetuximab showed additive effects, suggesting a potential therapeutic strategy for MET-driven resistance in lung cancer." (PMID 41050078, 2025). "Analysis of tissue samples from a patient with lung cancer revealed acquired resistance to erlotinib, where aside from T790 M mutation and MET amplification, no other resistance mechanisms were identified." (PMID 39531371, 2025). "Such scenarios relate to biomarkers and testing in lung cancer, small cell lung cancer, EGFR mutations and targeted therapy in non-small cell lung cancer (NSCLC), early-stage NSCLC, KRAS/BRAF/MET and other genomic alterations in NSCLC, and immunotherapy in advanced NSCLC." (PMID 39237103, 2025). "Equally important will be the search for predictive biomarkers to identify patients most likely to benefit; lessons from NSCLC, where HER2 mutations and c-MET overexpression have defined ADC activity, illustrate the potential for biomarker-driven selection in lung cancer and eventually also in SCLC." (PMID 41052285, 2025). "Antibodies binding MET are detected in a subset of patients with breast and lung cancer." (PMID 40401526, 2025). "While the downregulation of MET signaling is a target for lung cancer, enhanced shedding leading to dysregulated signaling might promote epithelium remodeling in eCOPD patients." (PMID 39766355, 2024). "In addition to total protein levels, ligand-activated MET, identified by phosphorylated MET (p-MET), is present in approximately two-thirds of lung cancer samples." (PMID 39201787, 2024). "In this retrospective study, a total of 47 MET fusions with an intact kinase domain (KD) were detected in 44 lung cancer patients whose baseline and/or post-treatment samples underwent capture-based hybrid targeted next-generation sequencing (NGS) between April 2016 and December 2021." (PMID 37588206, 2024). "The co-expression of EGFR and MUC1 was higher in tumor cells than EGFR combined with targets under active drug development for lung cancer such as MET, HER3 (ERBB3) or Trop2 (TACSTD2), suggesting the potential safety advantage of developing therapies targeting EGFR and MUC1." (PMID 39664199, 2024). "Furthermore, it was shown that p27 is downregulated in lung cancer cells resistant to MET inhibitor." (PMID 39175042, 2024). "Resistance to EGFR TKIs in lung cancer patients is commonly determined by MET amplification." (PMID 38675409, 2024). "In lung cancer, MET can form heterodimers with RTKs such as EGFR, HER2, HER3, and RET." (PMID 39201787, 2024). "The development of single-chain bispecific diabodies targeting c-MET and PD-1 for solid tumors has yielded notable effects, particularly in suppressing HGF/c-MET signaling, migration, and invasion of c-MET+ lung cancer and HCC cell lines such as A549 and MHCC-97H, respectively." (PMID 39664377, 2024). "Our extensive interrogation of the spatial and temporal heterogeneity of MET pathway activation upon osimertinib resistance in EGFR-mutant lung cancer may also explain other recent findings from the TATTON study." (PMID 38276867, 2024). "Therefore, targeting the HGF/MET axis in EGFR TKI-resistant lung cancer has emerged as a promising strategy to overcome EGFR TKI resistance." (PMID 38338342, 2024). "For instance, both mutation and high amplification could be detected in EGFR, MET, and ERBB2 in lung cancer, as well as mutations in KRAS, BRAF, STK11, KEAP1 and many others." (PMID 39289779, 2024).
lung cancer (continued). "We previously reported that the lung cancer compact panel TM (LCCP) could detect EGFR and MET gene mutations with sputum cytology." (PMID 37510070, 2023). "With MET amplification serving as a general resistance mechanism to targeted therapies in lung cancer, it is crucial to be able to detect MET amplification in a reliable manner, in order to identify the appropriate patients who can benefit from MET-targeting therapy." (PMID 36765572, 2023). "MET KDD was exclusively found in lung cancer, while FGFR2 KDD was first observed in gastric cancer." (PMID 36325957, 2023). "MET is a proto-oncogene commonly found in lung cancer patients." (PMID 36937524, 2023). "The formation of the HER3/MET heterodimer was reported in human lung cancer cells." (PMID 36751113, 2023). "MET tyrosine kinase inhibitors have been studied as potential lung cancer therapeutic agents." (PMID 37345192, 2023). "However, MET fusions are rare in lung cancer, and a systematic analysis of patients harboring this kind of genomic alteration is lacking." (PMID 36829199, 2023). "Moreover, genistein (5, 10, 25, 50, 100 and 200 μM) exerted anti‐cancer effects on the A549 human lung cancer cell by regulating Cas‐3/9 activity, miRNA27a activity and the expression of the MET protein." (PMID 37697969, 2023). "It was reported that the treatment with HDAC as an inhibitor of lung cancer cells could induce the expression of repressed miR-1 by the downregulation of oncogenes such as MET, PIM1, FOXP1, and HDAC4." (PMID 37569812, 2023). "Unecritinib also displayed notable growth inhibitory effects on several cancer cell lines carrying ALK rearrangements or mutations or overexpressing c-MET, with an IC50 of 180 to 378.9 nm for lung cancer cells and an IC50 of 23.5 nm for gastric cancer cells overexpressing c-MET." (PMID 37385995, 2023). "After transfection of A549, a human lung carcinoma cell line, with the appropriate gRNA-plasmid, followed by puromycin selection and limiting dilution cloning, we obtained several clones that were analyzed for MET expression by an ELISA assay." (PMID 37345079, 2023). "This budget may double in the case of NSCLC analysis, because lung carcinomas have to be additionally tested for EGFR, BRAF, KRAS, MET, and HER2 mutations as well as ALK, ROS1, and RET translocations." (PMID 37762506, 2023). "Cancer cell dissemination was assessed in vivo, evaluating: (i) the ability of MET−/− lung carcinoma cells to colonize the lungs following intravenous injection and (ii) the spontaneous dissemination to distant organs of MET−/− pancreatic carcinoma cells upon orthotopic injection." (PMID 37345079, 2023). "Dysregulation of the HGF/c-MET signaling cascade can lead to tumorigenesis by transforming normal cells into tumor cells and c-MET hyperactivation has been reported in cancers including lung cancer, colorectal cancer, glioblastoma, and acute myeloid lymphoma among others." (PMID 35778602, 2022). "Among the detected alternations, the eight-major driver mutations of lung cancer (EGFR, ALK, ERBB2, MET, RET, ROS1, BRAF, and KRAS) could be found in 14 out of 17 (82.4%) patients using both surgical and CNB specimens." (PMID 36224661, 2022). "It was demonstrated that Licochalcone D could induce ROS-dependent apoptosis in lung cancer cells by inhibiting c-MET, suggesting that c-MET is closely related to the redox system." (PMID 35693705, 2022). "We postulated that FAM83A-AS1 played an oncogenic role in lung cancer progression and cell autophagy regulation may be through MET-AMPKα signaling." (PMID 35635086, 2022). "A previous study indicated that treatment of Capmatinib over a period (e.g., 24 h) led to a dose-dependent increase of HER3 protein even though Capamtinib had the ability to suppress phosphorylation of EGFR and HER3 effectively in MET amplified H1993 lung cancer cells." (PMID 34974522, 2022).